RNU6-1171P (RNA, U6 small nuclear 1171, pseudogene)
Gene: Small nuclear RNA gene on chromosome 1 (148,739,379 to 148,739,479, forward strand). Ensembl gene ENSG00000252515.
Homologues: Orthologues: chimpanzee U6 (99% identical), macaque U6 (96% identical), guinea pig U6 (83% identical), rat LOC120096740 (82% identical), pig U6 (76% identical), pig U6 (69% identical). Paralogues in human: RNU6-1071P (100% identical), RNU6-465P (100% identical), RNU6-1042P (91% identical), RNU6-891P (91% identical), RNU6-15P (90% identical), RNU6-698P (90% identical), RNU6-831P (90% identical), RNU6-1060P (89% identical), RNU6-1145P (89% identical), RNU6-116P (89% identical), RNU6-166P (89% identical), RNU6-25P (89% identical), and 1288 more.